KRAS (KRas proto-oncogene, GTPase)
Diseases named in the same sentence as KRAS in open-access papers (continued):
Sharing a sentence is not in itself a finding about the gene and the disease.
adenocarcinoma (continued). "In addition, the frequencies of KRAS and GNAS mutations in IPMNs are highly variable according to the microscopic duct subtypes, reflecting their independent roles in the IPMN-adenocarcinoma sequence." (PMID 27512631, 2016). "KRAS mutations are present in 25–40% of adenocarcinoma patients, and these mutations are rarely observed in never-smokers." (PMID 26332764, 2015). "Moreover, RelB was overexpressed in both mutant KRAS-induced hyperplastic lesions and adenocarcinomas." (PMID 26147201, 2015). "One adenocarcinoma was wild type for KRAS, EGFR and EML4-ALK genomic alterations." (PMID 25360587, 2014). "However, oncogenic KRAS expression in mice induces adenocarcinomas, suggesting additional KRAS-activated pathways cooperate with sustained RAF-MEK-ERK signalling to bypass the oncogene-induced senescence proliferation arrest." (PMID 24489653, 2014). "Specifically, EGFR-mutated adenocarcinomas are more common in individuals who have never smoked, while KRAS-mutated adenocarcinomas occur more frequently among heavy smokers." (PMID 24179496, 2013). "Moreover, our results suggest that the overall genomic and transcriptional landscape of adenocarcinoma is only to a minor extent affected by the mutational status of EGFR and KRAS." (PMID 24205279, 2013). "In 158 EGFR and KRAS mutation-negative adenocarcinomas, 8 cases (5.1%) with iScore 3 and 150 cases with iScore 0 were identified." (PMID 23936355, 2013). "Moreover, constitutively active KRAS and β-catenin in the peripheral Clara cells lead to more aggressive adenocarcinomas by inducing a switch to an embryonic progenitor phenotype, indicating a role of β-catenin in the peripheral cells." (PMID 23224985, 2013). "In the univariate analysis, women, younger patients (<65 years), never smokers, and patients with adenocarcinoma, relapsed disease after curative operation, KRAS wild type tumors, and EGFR mutation tumors were associated with longer survival." (PMID 23724098, 2013). "This diagnostic algorithm was validated in 158 patients with EGFR and KRAS mutation-negative adenocarcinoma." (PMID 23936355, 2013). "ALK-positivity rates in the present study, 2.8% in the whole population and 5.1% in the group of EGFR and KRAS mutation-negative adenocarcinomas are consistent with those obtained in the many previous studies." (PMID 23936355, 2013). "EGFR mutations are more commonly identified in the adenocarcinomas of never smokers, while KRAS mutations are more frequent in heavy smokers." (PMID 24179496, 2013). "KRAS mutations are more common in adenocarcinomas and smokers and are reported in 15–30% without any pronounced ethnical differences." (PMID 26316935, 2012). "Our results are consistent with previous studies where ALK rearrangements have been largely (but not completely) restricted to adenocarcinomas that lack EGFR or KRAS mutations." (PMID 23198868, 2012). "In this series, KRAS mutations were not identified in any of the adenocarcinomas arising from the mid-portion of the bile duct or the intra-pancreatic portion of the bile duct." (PMID 21303542, 2011). "KRAS mutations were more frequent in serrated adenocarcinomas (45.2%) than in non-serrated adenocarcinomas (27.1%; P = 0.002)." (PMID 21457162, 2011). "Therefore, it is likely that many CRCs with the KRAS c12 G→A transversion represent serrated adenocarcinomas." (PMID 21457162, 2011). "A high frequency of the EML4-ALK fusion gene was present in Chinese patients with NSCLC, particularly in patients with adenocarcinomas without EGFR/KRAS mutations." (PMID 20624322, 2010). "The EML4-ALK fusion gene was present at a high frequency in Chinese NSCLC patients, particularly in those with adenocarcinomas lacking EGFR/KRAS mutations." (PMID 20624322, 2010). "The EML4-ALK fusion was associated with non-smokers (P = 0.03), younger age of onset (P = 0.03), and adenocarcinomas without EGFR/KRAS mutations (P = 0.04)." (PMID 20624322, 2010).
adenocarcinoma (continued). "CNGs were relatively frequent for EGFR and KRAS in adenocarcinomas." (PMID 19238210, 2009). "Interestingly, EGFR and KRAS mutations appear to be more prevalent not only in adenocarcinoma, but also in Asian patients, women, and nonsmokers." (PMID 38750337, 2024). "There were no typical mesonephric-like adenocarcinomas in 48 patients with KRAS mutations." (PMID 36797358, 2023). "The molecular classification of adenocarcinoma subgroup is established and is well known, where the most frequent genetic alteration among non-Asian patients is KRAS mutation (1/3) followed by EGFR (5%–15%) while in Asian patients EGFR mutation is the most frequent followed by KRAS mutation." (PMID 38239281, 2023). "The KRAS mutation detection rate in blood and tissue samples might differ among patients with mucinous and nonmucinous adenocarcinoma." (PMID 37751775, 2023). "Kirsten rat sarcoma viral oncogene homolog (KRAS) is one of the most commonly mutated oncogenes in NSCLC, with a mutation incidence of approximately 25% in Western populations; however, the incidence of KRAS mutation in adenocarcinoma in the Asian population is 5–15%." (PMID 36915627, 2023). "A different genetic profile emerged from the molecular analysis of the two additional adenocarcinoma nodules I3 and S1, lacking those somatic mutations identified in the mixed nodules, but shared two somatic missense mutations in the KRAS (p.Gly12Asp) and NOTCH1 (p.Pro498Arg)." (PMID 34926584, 2021). "In the multivariate logistic regression analysis, non-adenocarcinoma (OR, 1.553; P = 0.035), right colon (OR, 1.626; P = 0.008), well and moderate differentiation (OR, 2.227; P = 0.002) and positive CA19-9 (OR, 1.591; P = 0.030) were independent factors for predicting KRAS mutations." (PMID 34221952, 2021). "Early studies found that the mutation frequency of EGFR was lower than other adenocarcinomas (undetectable to ~28% in IMA vs. 47%–78% in non-IMA patients), while the frequency of KRAS mutations was higherin IMA than other adenocarcinomas (14%–86% in IMA vs. 1.5%–17% in non-IMA patients)." (PMID 33505917, 2020). "EGFR mutations were affected significantly more frequently in B7-H3 negative adenocarcinomas than in B7-H3 positive adenocarcinomas, while KRAS mutations were affected significantly more frequently in B7-H3 positive adenocarcinomas than in B7-H3 negative adenocarcinomas (*, p < 0.05)." (PMID 30513627, 2018). "Importantly, this was not the case for the MPE of the KRAS mutated but EGFR wild-type adenocarcinoma." (PMID 27548442, 2016).
adenocarcinoma (continued). "In addition, if it is needed, narrowing -down to patients with EGFR and KRAS mutation-negative adenocarcinomas seems rational, resulting in minimal risk for an inappropriate exclusion of potentially positive patients." (PMID 23936355, 2013). "However, the corresponding gender difference was not significant for KRAS-mutated adenocarcinoma (P=0.802)." (PMID 24179496, 2013). "EGFR-mutated adenocarcinomas were more common in female never smokers than KRAS mutations." (PMID 24179496, 2013). "Among non-serrated adenocarcinomas, KRAS c12/13 and c59 mutations were found in 16 cases." (PMID 21457162, 2011). "Notably, the frequency of ALK fusions in patients with adenocarcinomas that did not exhibit EGFR/KRAS mutations reached 45.0% (9/21), strongly indicating that only a specific molecular subset of adenocarcinomas is characterized by EML4-ALK fusion." (PMID 20624322, 2010). "Notably, the presence of ALK fusions was associated with histological adenocarcinomas and with wild-type EGFR and KRAS status, which may be of clinical relevance in targeted therapy using ALK inhibitors." (PMID 20624322, 2010). "These mutations consisted of 19 KRAS (24.7%), 10 EGFR (13%), five BRAF (6.5%), four PIK3CA (5.2%), one HER2 (1.3%), one HER4 (2.2%) and none for HER3. mEGFR, mBRAF and mHER2 were present exclusively in adenocarcinomas while mKRAS were more frequent in adenocarcinoma and large cell histologies." (PMID 19238210, 2009). "Table II may be of assistance in respect of KRAS and EGFR mutational status in adenocarcinoma." (PMID 19672420, 2009). "The adenocarcinoma samples that had EGFR mutations did not present with KRAS mutations." (PMID 17184525, 2006). "Together, these data suggest that RAS stability is differentially regulated in hematologic cancers versus adenocarcinomas and further support the notion that PPP1R2/PP1C/LZTR1-dependent regulation of KRAS stability is a feature of hematologic cancers." (PMID 41542462, 2026). "KRAS-G12C and PIK3CA-Q546K were identified in 92.3% and 38.4% of 13 MAP adenocarcinomas, respectively." (PMID 42164324, 2026). "One of the most significant advancements has been in targeting the Kirsten rat sarcoma viral oncogene homolog (KRAS) gene, which plays a critical role in NSCLC, particularly adenocarcinomas." (PMID 39996842, 2025). "For example, in lung tissues from KRAS G12D mutant mice and early‐stage NSCLC adenocarcinoma patients, senescent alveolar macrophages with high p16 and CXCR1 expression accumulated." (PMID 40485603, 2025). "Within adenocarcinoma, exploratory molecular subgroups showed: EGFR 10/18 (55.6%) brain; KRAS 4/9 (44.4%) liver; ALK 3/3 (100%) bone." (PMID 41294679, 2025). "In contrast, mixed well-to-poorly differentiated adenocarcinomas were less frequent in the BRAF/NRAS group (three of six cases, 50.0%) than in the KRAS (33 of 39 cases, 84.6%) or WT (21 of 27 cases, 77.7%) groups." (PMID 41439081, 2025). "KRAS is the most prevalent oncogenic alteration in NSCLC, occurring in approximately 30% of adenocarcinoma cases." (PMID 40936915, 2025). "In adenocarcinoma subgroups, EGFR-mutant tumors most often metastasized to the brain (55.6%), KRAS-mutant tumors to the liver (44.4%), and ALK-rearranged tumors to bone (100%)." (PMID 41294679, 2025). "In some NSCLC patients, mainly adenocarcinoma, molecular alterations in driver genes, like EGFR, KRAS, HER2, ALK, MET, BRAF, RET,ROS1, and NTRK are recognized." (PMID 37346803, 2023). "Colonic adenocarcinomas that were BRAF and KRAS wild types had moderate to strong nuclear staining, and weak to negative cytoplasmic staining." (PMID 34201061, 2021). "However, our model could represent the portion of human adenocarcinomas negative for KRAS and EGFR mutations." (PMID 29415661, 2018).
adenocarcinoma (continued). "A significant positive correlation between miR-30c and KRAS or ELK1 was observed in the 21 lung tumor samples (P = 0.0229 and P = 0.0011, respectively) and between miR-21 and ELK1 in 160 adenocarcinoma samples from the TCGA (LUAD data set)." (PMID 29440633, 2018). "In the adenocarcinoma stage, we found that the essentiality of ERK was significantly increased since it reduces the abnormal proliferative phenotype elevated by KRAS over-expression." (PMID 27765040, 2016). "In general, NSCLC have more often activating mutations in important growth factor receptor signaling genes like EGFR and KRAS, although the percentage is lower in squamous cell NSCLC compared with adenocarcinoma NSCLC." (PMID 28031935, 2016). "The TT group was predominantly stage IV (51.7%), had adenocarcinoma histology (69.0%), poorly differentiated grade (54.7%), a smoking habit (77.9%), ECOG-PS of 0 (47.6%) and a wild-type status of KRAS (77.9%)." (PMID 26573509, 2015). "A number of adenocarcinoma-specific gene alterations are known, including EGFR, KRAS and BRAF, and these affect the gene products of the MAP kinase and PI3/AKT signaling pathways." (PMID 25364428, 2014). "Several of the identified mGISTIC regions harbored known or putative adenocarcinoma driver candidates, such as EGFR, MDM2, KRAS, MYC, TERT, MET, CCND1, NKX2-1/TITF1, CDK4, ERBB2, ID1, RB1, CDKN2A and PTEN." (PMID 24205279, 2013). "The three most frequently altered genes in a subgroup of smokers with adenocarcinoma were EGFR (22.0%), STK11 (19.0%), and KRAS (12.0%)." (PMID 22768234, 2012). "KRAS and EGFR play pivotal roles in the development and growth of NSCLC, especially in patients with adenocarcinoma histology." (PMID 22992338, 2012). "Importantly, actionable KRAS and EGFR alterations make up a significant portion of overall actionable alterations in advanced NSCLC (adenocarcinoma), together accounting for 44% in Western populations and up to 60% in Asian populations." (PMID 40282516, 2025). "In Western countries, mutations in the Kirsten rat sarcoma viral oncogene homolog (KRAS) gene are the most identified driver mutation in non-squamous NSCLC, presenting in approximately 30% of adenocarcinoma cases." (PMID 41007704, 2025). "We report a 76-year-old non-smoking Japanese woman diagnosed with adenocarcinoma confirmed as KRAS G12D/S-positive." (PMID 40218244, 2025). "The third NSCLC patient with SD was immune checkpoint inhibitor-naïve, had PD-L1 negative adenocarcinoma, and no KRAS/STK11/KEAP1 alteration was seen." (PMID 41523436, 2025). "This discrepancy reflects variations in diagnostic protocols: while ICS Maugeri did not routinely screen for KRAS mutations, CC-HRH systematically tested all adenocarcinoma cases." (PMID 41008841, 2025). "Since KRAS and EGFR mutational status were examined in only 29.5% (13/44) and 9.1% (4/44) of the patients with adenocarcinoma enrolled in this study, respectively, they were not included as study variables in logistic regression." (PMID 38504315, 2024). "We analyzed the difference in the KRAS mutation detection rate with liquid NGS between nonmucinous and mucinous histological types, including adenocarcinoma." (PMID 37751775, 2023). "The KRAS and EGFR pathways in adenocarcinoma are mutually exclusive, which suggests different molecular pathways being implicated in the development of adenocarcinoma between smokers and non-smokers." (PMID 36661704, 2023). "Only one patient (5.3%) with KRAS‐positive nonmucinous adenocarcinoma and lung metastasis had a positive blood sample." (PMID 37751775, 2023). "Of these patients, only one was diagnosed with nonmucinous adenocarcinoma and only one patient was liquid KRAS‐positive." (PMID 37751775, 2023).
adenocarcinoma (continued). "Therefore, in the oncogenic KRAS-mediated transformed club cells, USP13 seems to prevent those club cells from adopting an AT2-like adenocarcinoma identity, instead switching the fate of cells to squamous cell traits." (PMID 38093367, 2023). "It is also conceivable that DARPP-32 might contribute to TKI therapy-refractory growth in adenocarcinomas in which additional downstream genetic alterations exist in genes like RET, ALK, BRAF, or KRAS, although such studies are yet to be conducted." (PMID 34675407, 2022). "KRAS mutations were detected more often in IMA and no KRAS mutations were observed in micropapillary predominant adenocarcinoma." (PMID 34026636, 2021). "For example, in our cohort, canonical oncodriver mutations were identified in three of the six tumors with an adenocarcinoma component (SOS1 in Pa34, EGFR/PIK3CA in Pa35, and KRAS/PIK3CA in Pa37) compared to pure LUADs, the majority of which harbor driver mutations." (PMID 34873156, 2021). "ALK-positive NSCLC patients were mostly non-smokers or light smokers and relatively young, had adenocarcinoma, and generally did not exhibit gene mutations such as the EGFR and Kirsten rat sarcoma viral oncogene homolog (KRAS) mutations." (PMID 32882995, 2020). "In contrast, a subset of LAD patients remain without EGFR, KRAS, and ALK mutations (triple-negative (TN) adenocarcinomas)." (PMID 31093306, 2019). "Among HER2-overexpressing adenocarcinomas, 1 (16.7%) and 2 (33.3%) had EGFR and KRAS mutations, respectively, while none had ALK or ROS1 rearrangements." (PMID 28146588, 2017). "VAMP2-NRG1 was reported in a 67-year-old never-smoker woman with adenocarcinoma with no mutation in EGFR, KRAS and BRAF and with no fusion genes involving ALK, ROS1 or RET." (PMID 27626312, 2016). "KRAS mutation was present in 190 (64 %) of 297 IPMN patients with invasive adenocarcinoma, whereas 388 (63 %) of 620 IPMNs without adenocarcinoma." (PMID 27512631, 2016). "Likewise, a KRAS p.12G>C substitution was spotted in three AAH lesions and primary adenocarcinoma within the same lung, indicating that KRAS mutation is also an early transformation-driving event in multistep progression." (PMID 26374070, 2015). "Similarly, the TG/GG patients were predominantly stage IV (54.8%), with adenocarcinoma histology (74.2%), poorly differentiated grade (65.0%), smoking habit (71.0%), ECOG-PS of 0 (58.1%) and a wild-type status of KRAS (64.5%)." (PMID 26573509, 2015). "ALK rearrangement was identified in 2 patients (1.0%) from the test set and both adenocarcinomas were negative for EGFR and KRAS mutations." (PMID 23936355, 2013). "In a subgroup of non-smokers with adenocarcinoma, EGFR was the most frequently altered gene, with a mutation rate of 49.8%, followed by EML4-ALK (9.3%), PTEN (9.1%), PIK3CA (5.2%), c-Met (4.8%), KRAS (4.5%), STK11 (2.7%), and BRAF (1.9%)." (PMID 22768234, 2012). "The fusions occurred predominantly in adenocarcinomas from never smokers and were mutually exclusive of mutations in EGFR, KRAS, and ALK." (PMID 22928112, 2012). "The clinical features of lung cancer that harbors EML4-ALK include light- or never-smokers, younger age, adenocarcinomas with acinar pattern or signet ring adenocarcinoma, and a lack of EGFR or KRAS mutations." (PMID 23181703, 2012). "KRAS c12/13 mutations in serrated adenocarcinomas were never accompanied by MSI-H, in contrast to 15/27 (55.6%) of MSS/MSI-L cases harbouring a KRAS mutation (P = 0.075)." (PMID 21457162, 2011). "KRAS and BRAF mutations were observed in 45% and 33% of serrated adenocarcinomas and in 27% and 0% of non-serrated CRCs (P < 0.001)." (PMID 21457162, 2011).